RUNX2 (RUNX family transcription factor 2)
Diseases named in the same sentence as RUNX2 in open-access papers (continued):
Sharing a sentence is not in itself a finding about the gene and the disease.
prostate carcinoma (102 papers, 2007 to 2025). A carcinoma that arises from epithelial cells of the prostate gland. "RUNX2 overexpression in breast and prostate cancer cells is associated with EMT and a specific metastatic phenotype known as osteomimicry, allowing cells to metastasize to bone." (PMID 38630262, 2024). "RUNX2 was overexpressed in breast and prostate cancer and associated with increased metastatic capacity." (PMID 36092942, 2022). "RUNX2 overexpression is associated with an increase in bone metastasis of breast cancers and prostate cancers." (PMID 36231060, 2022). "Gupta and coworkers demonstrated that Integrin αvβ3 and CD44 are involved in prostate cancer patients bone loss by promoting osteoclastogenesis through the RUNX2/Smad 5/receptor activator of NF-κB ligand pathways." (PMID 32204402, 2020). "Runx2, an essential “master regulator” for bone formation, is abnormally expressed in aggressive breast and prostate cancer and activates genes associated with tumorigenesis and metastasis." (PMID 27634876, 2016). "Transcriptome profile showed that RUNX2 was associated with the malignant behavior of prostate cancer, including invasion and bone spread by up-regulating MMP9, SNAI2 and Smad3." (PMID 27007162, 2016). "In prostate cancer, RUNX2 was associated with skeletal destruction by enhancing the expression of metastasis-related proteins MMP9 and MMP13." (PMID 27007162, 2016). "Our study, for the first time, identifies changes in Runx1 and Runx2 that are associated with molecular markers of human prostate cancer progression." (PMID 27634876, 2016). "Runt-related transcription factor 2 (RUNX2) is positively associated with tumor progression in prostate cancer." (PMID 24713112, 2014). "Additionally, it has been shown that the abnormally higher RUNX2 expression level in prostate cancer tissues is positively associated with their stage and aggressiveness." (PMID 29558908, 2018). "Using the TRAMP mouse model of human prostate cancer, we address mechanisms of deregulation for the cancer-associated transcription factors, Runx1 and Runx2 by identifying microRNAs with reciprocal expression changes at six time points during 33 weeks of tumorigenesis." (PMID 27634876, 2016). "Thus, loss of RUNX2 in this context might permit osteomimetic prostate cancer cells to gain a proliferative advantage subsequent to seeding in the bone environment." (PMID 31136607, 2019). "To assess the generalizability of this correlation, we analyzed the correlation between RUNX2 and a gene signature composed of the identified lipid-related targets using TC, BC, and prostate cancer datasets from TCGA." (PMID 41174748, 2025). "mir-466c regulates Vegfa expression in a state of hypoxia in endothelial cells and suppresses Runx2 to inhibit prostate cancer." (PMID 38674332, 2024). "RUNX2 phosphorylation plays a crucial role in the occurrence and development of prostate cancer, inducing tumor cells to develop an invasive phenotype, which ultimately contributes to their metastasis." (PMID 38430423, 2024). "As RUNX2 is a widely known vital marker and driver in bone metastatic prostate cancer, this CCNL1/CDK19/NEAT1-1 complex can significantly induce the bone metastasis of prostate cancer." (PMID 37069649, 2023). "Overexpressing RUNX2 in implanted prostate cancer cells activated genes required for osteolytic illness, such as PTH-related protein (PTHrP) and interleukin 8 (IL8)." (PMID 37370857, 2023). "RUNX2 is an established driver of bone metastasis prostate cancer, thus strengthening the central role of m6A-NEAT1 in prostate cancer bone metastasis." (PMID 36969033, 2023). "In prostate cancer, the increased expression of RUNX2 under nitric oxide conditions conferred resistance to docetaxel in LNCaP cells, and activation of the ERK-PI3K-AP1-RUNX2 axis was indicated." (PMID 37108164, 2023). "RUNX2 overexpression in prostate cancer LNCaP cells increased tumor angiogenesis and oxygenation in vivo in a xenograft model." (PMID 37108164, 2023).
prostate carcinoma (continued). "All these studies consequently suggest that RUNX2 has a proangiogenic role in promoting the early steps of tumorigenesis, and is probably involved in driving bone metastasis in breast and prostate cancers." (PMID 36231060, 2022). "In prostate cancer, activation of RUNX2 promotes tumor microenvironment modification, which promotes carcinogenesis and disease progression." (PMID 35522574, 2022). "Similar results have also been found in lymphomas and prostate cancer, where low apoptotic rates have been detected related to overexpression of RUNX2 and genes such as Myc and BCL2." (PMID 36510562, 2022). "In prostate cancer, it has been described that RUNX2 can bind to the promoter region of antiapoptotic genes and regulate their expression through the recruitment of other cofactors, such as BCL2." (PMID 36510562, 2022). "The SOX4 gene has been identified as a critical component of the PTEN-PI3K-AKT pathway in prostate cancer, and RUNX2 is a type of oncogene that unusually increases in prostate cancer cells, promoting their metastatic phenotype." (PMID 34512726, 2021). "This gene can decrease the migration and invasion of prostate carcinoma cells by interacting with Runx2." (PMID 34511023, 2021). "Akech and colleagues observed elevated osteolysis in response to increased Runx2 expression using three distinct sublines of the bone metastatic prostate cancer PC3 cells which express varying levels of Runx2." (PMID 34503118, 2021). "RUNX2, in turn, plays an important role in prostate cancer cells, and its expression was shown to be regulated via a PTEN/AKT/forkhead box protein O1 (FOXO1) axis." (PMID 34064589, 2021). "Among these hsa-miR-204-5p target genes, SIRT1, SOX4, and RUNX2 exhibited a tumor-suppressive/oncogenic role in previous prostate cancer studies." (PMID 34512726, 2021). "RUNX2 nuclear localization was increased in prostate cancer tissue sections, indicative of a possible predictor of prostate cancer metastasis." (PMID 33062960, 2020). "RUNX2 is abnormally expressed in prostate cancer cells (PC3) and, to a lesser extent, in LNCaP cells." (PMID 33062960, 2020). "With the RUNX2 and related pathway, bone metastatic prostate cancer exhibited the similar features with bone and can be survival in the environment of bone." (PMID 33308223, 2020). "FOXO4 has also been identified by a genome-wide RNAi screen to be a suppressor of metastasis through antagonising PI3K/AKT signal pathway and RUNX2-dependent transcription in prostate cancer." (PMID 32372224, 2020). "miR-466 regulates its target gene RUNX2 to inhibit bone metastasis and tumor growth in prostate cancer." (PMID 33111744, 2020). "This study aimed to determine the biological consequence of CD44 cleavage and its potential interaction with Runt-related transcription factor (RUNX2) in a sequence-specific manner in PC3 prostate cancer cells." (PMID 33062960, 2020). "We first reconfirmed the expression levels of CD44, CD44-ICD, and RUNX2 in three significant prostate cancer cell lines (LNCaP, PC3, and PCa2b)." (PMID 33062960, 2020). "Functionally, overexpression of this miRNA in the PC3 prostate carcinoma cell line significantly reduces the expression of RUNX2 at the protein level." (PMID 32230926, 2020). "At the molecular level, a study shows that the Akt signalling pathway suppresses cell migration and invasion through FOXO1 to inhibit runt-related transcription factor 2 (RUNX2) transcriptional activity in prostate cancer." (PMID 32372224, 2020). "In human prostate cancer LNCaP cells, NO upregulates RUNX2 and Bcl2 expression which confers resistance to chemotherapy." (PMID 30972102, 2019). "RUNX2 is a bone-specific transcriptional regulator, aberrantly expressed in metastatic prostate cancer cells and BIRC2, also known as Inhibitor of Apoptosis (IAP) plays key role in drug resistance and survival of cancer cells through inhibition of apoptosis." (PMID 31756185, 2019).
prostate carcinoma (continued). "Though RUNX2 is highly expressed in metastatic breast and prostate cancer cells, its expression in the normal breast or prostate epithelial cells is negligible." (PMID 31331331, 2019). "RUNX2 overexpression in breast or prostate cancer increases metastasis of these cancer cells to bone." (PMID 31331331, 2019). "In prostate cancer, miR-466, by directly repressing the osteogenic transcription factor RUNX2, inhibits tumor growth and metastases, highlighting the role of RUNX2 in inducing the malignant phenotype." (PMID 30463392, 2018). "Inhibition of Runx2 in metastatic breast and prostate cancer cells drastically reduces tumor growth and metastasis in vivo, revealing Runx2 function as an oncogene." (PMID 28407681, 2017). "We further demonstrated that miR-466 partially exerted these effects by directly targeting runt-related RUNX2, a master osteogenic transcription factor and attenuated its downstream target genes that are known to mediate prostate cancer bone metastasis." (PMID 28125091, 2017). "Here we report use of miR-466 as a potentially novel avenue to regulate RUNX2 and its downstream genes, thereby inhibiting prostate cancer growth and bone metastasis." (PMID 28125091, 2017). "Using the TRAMP-C2 cell line, which provides an in vitro model to elucidate molecular mechanisms of prostate cancer, we assessed the functional activities of Runx1 and Runx2 in PCa." (PMID 27634876, 2016). "The persistent elevation of Runx1 and Runx2 transcription factors in TRAMP prostate tissue throughout progression to adenocarcinoma suggests a pro-tumorigenic role in prostate cancer." (PMID 27634876, 2016). "Some evidence indicates a role for RUNX2 in T-cell lymphoma, acute myeloid leukemia and multiple myeloma and bone metastasis in advanced mammary and prostate cancer." (PMID 26204939, 2015). "RUNX2 siRNA treatment of the prostate cancer cell line PC3 decreases migration and invasion through Matrigel in vitro." (PMID 26204939, 2015). "As described, the expression level of RUNX2 was higher in a variety of human cancer tissues including prostate cancer than that in their corresponding normal ones." (PMID 26512706, 2015). "In androgen-independent prostate cancer cell lines, knocking down or overexpressing RUNX2 leads to a decreased or increased level of phosphorylated AKT at serine 473 (pAKTS473) respectively by mechanisms yet to be defined." (PMID 26204939, 2015). "Intriguingly, CSCs enriched from prostate cancer tissues highly expressed RUNX2 as well as its target gene Survivin." (PMID 26512706, 2015). "Recent studies revealed that RUNX2-mdiated carcinogenesis is dependent on the direct activation of survivin expression in prostate cancer cells." (PMID 26512706, 2015). "Runx2 is an osteoblast master transcription factor that is aberrantly expressed in prostate cancer cells and promotes their metastatic phenotype." (PMID 26575035, 2015). "FOXO1 interacts with RUNX2 in vitro and in prostate cancer cells, and inhibits RUNX2 transcriptional activity on the OP, IL8, VEGF and MMP13 genes." (PMID 26204939, 2015). "LC-MS/MS analysis of secreted proteins that are upregulated after RUNX2 overexpression in prostate cancer cells revealed increased expression of a number of proteins, including basement membrane components laminins A5 and B1." (PMID 24713112, 2014). "RUNX2 has been shown to play a key role in prostate cancer metastasis, but mostly in regards to crosstalk between CaP and bone cells during development of osteoblastic metastases." (PMID 24983969, 2014). "Upregulation of RUNX2 in cell lines correlates with increased invasiveness and the capacity to form osteolytic disease in models of breast and prostate cancer." (PMID 24626992, 2014). "In this regard, it was interesting to note that in the conditional Pten deletion model of prostate cancer, protein levels of BMPs, Runx2, and survivin all increase with the tumor growth, implicating a potentially central role of survivin in prostate cancer." (PMID 23936028, 2013).
prostate carcinoma (continued). "Taken together, our results indicate that the formation of the nuclear RUNX2/p-Smad 5 complex is a critical mechanism within metastatic prostate cancer cells to facilitate the expression of RANKL." (PMID 22966907, 2012). "Runx2 regulates early metastatic events in breast and prostate cancers, tumor growth, and osteolytic bone disease." (PMID 22966907, 2012). "To further validate the immunoblotting findings, we carried out immunohistochemistry analyses with antibodies to RANKL, RUNX2, Smad 5 and p-Smad 5 in a human prostate cancer tissue microarray (TMA)." (PMID 22966907, 2012). "FOXO1 is involved in prostate cancer cell migration and invasion as a critical negative regulator of Runx2." (PMID 23029264, 2012). "Although Runx proteins have tumor suppressor properties, recent studies assigned a role for Runx2 in promoting breast and prostate cancer metastasis." (PMID 22151997, 2011). "Consistent with the 'wound healing' assays presented here, studies using Boyden chambers have shown that RUNX2 is required for both cell migration and invasion through Matrigel in prostate cancer cells." (PMID 21029421, 2010). "Notably, in prostate cancer, particularly under conditions of bone metastasis, RUNX2 expression is significantly upregulated." (PMID 38430423, 2024). "In addition, recent studies have confirmed that RUNX2 is closely related to the proliferation and invasion of cancers, such as osteosarcoma, breast cancer, prostate cancer, gastric cancer, lung cancer, melanoma, and colorectal cancer." (PMID 36897488, 2023). "Nitric oxide (NO) is yet another regulator of RUNX2 expression in prostate cancer." (PMID 36231060, 2022). "Furthermore, gain-of-function studies of RUNX2 in prostate cancer cells identified several pro- and antiapoptotic genes differentially expressed in RUNX2-overexpressing cells compared to control cells." (PMID 36510562, 2022). "Furthermore, the pro-inflammatory arachidonic acid-derived prostaglandin E2 (PGE2) was shown to enhance the expression of the bone metastasis-promoting proteins MMP2, MMP9, RANKL, and RUNX2 in prostate cancer cells, partly via the PI3K/AKT pathway." (PMID 34064589, 2021). "RUNX2 may play a promoting role in invasive bone cancer, prostate cancer, pancreatic cancer, and GC." (PMID 33313404, 2020). "Interestingly, another study reported that bone-metastasis cells from prostate cancer also express RUNX2." (PMID 32230926, 2020). "RUNX2 is a central driver in bone metastatic prostate cancer." (PMID 33308223, 2020). "Furthermore, it was here demonstrated that through its ability to target both RUNX2 and Dlx5, miR-203 decreases the expression of osteopontin and osteocalcin in prostate cancer cells." (PMID 32230926, 2020). "Interestingly, ChIP assays in a prostate cancer model reveal that RUNX2 regulates survivin expression through its direct binding at consensus sequences in the survivin promoter." (PMID 32230926, 2020). "Besides, Toshihisa el al. also reported Runx2 plays an important role in the bone metastasis of breast and prostate cancers by up-regulating SPP1." (PMID 33365318, 2020). "Identification of the CD44-ICD sequences which have a higher affinity for RUNX2 is of great importance, and that may serve as a promising therapeutic target for prostate cancer metastasis." (PMID 31331331, 2019). "Indeed, reconstitution of miR-466 in metastatic prostate cancer cells significantly attenuated RUNX2 protein levels, suggesting a functional role of miR-466 in controlling RUNX2 protein translation." (PMID 28125091, 2017). "MiR-221 is established as a tumor suppressor for prostate cancer uniquely by targeting Runx2." (PMID 28061868, 2017). "Targeting RUNX2 in prostate cancer could interrupt an integrated network of gene expression required to maintain tumor growth and bone metastasis." (PMID 28125091, 2017). "Further, these factors may cooperate; AR/RUNX2 complexes are important drivers of prostate cancer stem cell expansion." (PMID 28412963, 2017).
prostate carcinoma (continued). "Thus, miRNAs that target Runx1 or Runx2 and are deregulated during prostate tumorigenesis present exciting candidates for novel therapeutic intervention in men diagnosed with prostate cancer." (PMID 27634876, 2016). "Our previous studies, and those of other laboratories, have documented the osteomimetic properties of Runx2 in primary tumors and that inhibition of Runx2 in breast and prostate cancer cells blocks metastasis and osteolytic bone disease mediated by human tumor cells in orthotopic mouse models." (PMID 27634876, 2016). "The expression of RUNX2 and androgen receptor (AR) predicts prostate cancer recurrence." (PMID 27007162, 2016). "FOXO1 also inhibits RUNX2-mediated migration and invasion of prostate cancer cells." (PMID 26204939, 2015). "Interestingly, expression of PTEN and the level of FOXO1 in the nucleus inversely correlate with RUNX2 expression in prostate cancer specimens from patients with lymph nodes or bone metastasis." (PMID 26204939, 2015). "Moreover, twinfilin was found to be upregulated in genome-wide mRNA expression changes in prostate cancer cells in response to Runx2." (PMID 26575035, 2015). "Furthermore, RUNX2-SMAD interaction is crucial for distal metastasis of prostate cancer cells from bone to lung." (PMID 26204939, 2015). "Of note, CSC-enriched fractions prepared from prostate cancer tissues highly expressed RUNX2 as well as its target gene Survivin, implying that RUNX2 might be associated with the biology of CSC in prostate cancer." (PMID 26512706, 2015). "However, the role of RUNX2 in promoting tumor development in mammary and prostate cancer extends beyond its pro-bone metastatic effects and the osteolytic disease associated with these cancers." (PMID 26204939, 2015). "Overexpression of RUNX2 in the prostate cancer cell line C4-2B enhances its invasiveness." (PMID 26204939, 2015). "Moreover, PC3c similarly to PC3 cells expressed factors known to be implicated in prostate cancer osteomimicry such as OPN and Runx2." (PMID 24069383, 2013). "Our results showing higher gene and protein expression levels of Runx2 in lung cancer cells compared to normal lung fibroblast cells are consistent with previous reports of Runx2 expression in other epithelial cancers like breast and prostate cancers." (PMID 22537242, 2012). "Runx2 nuclear localization was found to be up-regulated in prostate cancer and was suggested that this could be used as a predictor of metastasis in prostate cancer." (PMID 22966907, 2012). "Breast and prostate cancers over expressing RUNX2 metastasized predominantly to bone." (PMID 22966907, 2012). "RUNX2 is overexpressed in cancers that, like prostate cancer, metastasize to bone." (PMID 20021671, 2009). "Previous studies have shown that RUNX2 could be upregulated by hypoxia in prostate cancer." (PMID 35110544, 2022). "As Runx2 has been implicated in RANKL expression in various cell types, such as prostate cancer cells, vascular smooth muscle cells, and osteoblasts, we further examined whether CrkL-inhibited Tnfsf11 expression is involved in the regulation of Runx2 expression." (PMID 34209812, 2021). "Therefore, restoration of miR-466 to regulate an integrated network of RUNX2 and its target genes may represent a promising approach to suppress prostate cancer bone metastases." (PMID 28125091, 2017). "Thus, our data strongly suggests a miR-466 mediated attenuation of RUNX2 may be a novel approach to prevent bone metastatic disease in prostate cancer." (PMID 28125091, 2017). "However, based on immunoblotting analyses in PC3 nuclear lysates and human prostate cancer cells, we propose that RUNX2 localized in the nucleus of cancer tissue is mostly phosphorylated (lane 2); c) Diffuse distribution of Smad-5 was observed in normal and prostate carcinoma sections." (PMID 22966907, 2012).